CD4 (CD4 molecule)
Diseases named in the same sentence as CD4 in open-access papers (continued):
Sharing a sentence is not in itself a finding about the gene and the disease.
AIDS (continued). "The purpose of our investigation was to examine baseline VL and CD4 count among people aged ≥50 years at the time of recruitment and identify disparities, if any, by gender, age group, current residence, WHO staging, patient source, and marital status in patients attending HIV/AIDS clinic at KTRH." (PMID 34394214, 2020). "In 2016, the WHO updated the consolidated guidelines on the use of antiretroviral drugs for treating and preventing HIV infection, which proposed that all adults, adolescents and children with HIV/AIDS should receive ART regardless of CD4 counts and WHO clinical staging." (PMID 32210333, 2020). "Many studies have shown that a low CD4+ cell count, older age, male gender, clinical stage III/IV disease, low body mass index (BMI), and signs/symptoms of AIDS are independent factors related to death among patients on ART, indicating that patients with ADE may have higher mortality." (PMID 32680536, 2020). "In START, viral suppression at 12 months was 98% among individuals with CD4 counts >500 cells/μL who started ART immediately and 97% among those who waited to initiate ART (i.e. until the CD4 count dropped <350 cells/μL or they developed AIDS or another condition requiring ART)." (PMID 30746898, 2019). "We observed an effect of the advanced HIV/AIDS variable in IRIS females as compared with non-IRIS females (mean CD4+ T cell percentage 13.36 vs. 18.63%; P = 0.0489 and P < 0.05 by the multivariable analysis), underpinning the exclusively skewed distribution toward the female sex of this cohort." (PMID 31355171, 2019). "Late presentations to Human Immunodeficiency Virus/Acquired Immunodeficiency Syndrome (HIV/AIDS) care is defined as persons presenting for care with a CD4 cell count below 350 cells/μl or presenting with an AIDS-defining event, regardless of the CD4 cell count." (PMID 31208360, 2019). "The patients who developed BSI had lower CD4+ counts and higher frequency of late presenters when compared to the global population of PLWHIV without BSI, confirming the importance of immune recovery for also preventing bacterial infections other than those commonly codified as AIDS-defining." (PMID 30931978, 2019). "Among MSM, compared with ART deferral until a CD4+ less than 350 cells/μl or AIDS, a strategy of immediate ART had no impact on prevalence of HIV-serodifferent CLS (CLS-D) over the subsequent 2 years, or on related measures of frequency of such sex or partner numbers." (PMID 31764099, 2019). "None of the known determinants of survival in patients with AIDS-KS analysed in this study including age, gender, type of chemotherapy received, CD4 cell counts at the start of chemotherapy and early response to chemotherapy were significantly associated with survival." (PMID 31516547, 2019). "Since SHIV env genes are derived from HIV-1, we were motivated to investigate whether any of a large panel HIV-1 R5 Envs derived from AIDS patients could also infect CCR5-expressing cells without CD4." (PMID 30415390, 2019). "However, since the multivariable models were adjusted for time‐updated CD4 count and viral load, changes over time in the rate of non‐AIDS mortality are not entirely explained by CD4 count and viral load." (PMID 30615271, 2019). "All the results suggest that ablation of CCR5 via the CRISPR/SaCas9 system may be a safe alternative approach for generation of HIV-1 resistance in human CD4+ T cells and CD34+ HSPCs, however, there are also potential drawbacks in targeting CCR5 alone in HIV-1/AIDS gene therapy." (PMID 31186067, 2019). "Indeed, the increased IPD susceptibility of not only pediatric, but also AIDS adults (i.e., HIV-infected adults), with low CD4+ T-cells implies a protective role of CD4 T-cells independent of antibodies." (PMID 30669439, 2019).
AIDS (continued). "Although there was a weak trend for “Under 25, CD4<200” to reduce time-discounted AIDS deaths relative to “Under age 25” for Starg between 50 and 60% using a 7% discount rate, CD4-age hybrids did not reduce time-discounted AIDS deaths using the standard 3% discount rate." (PMID 31846456, 2019). "Interestingly, peripheral blood CD4+ T cell counts in sporadic PD are also depressed, though not as much as in AIDS." (PMID 31396143, 2019). "In addition, the higher anemia level by itself is also a good opportunity for progression of HIV/AIDS irrespective of CD4 counts level and viral load." (PMID 30941180, 2019). "This putative mechanism implies that poor CD4+ T cell-mediated control of Malassezia populations would be an important precipitating factor for PD and SD, occurring gradually in normal aging (through immunosenescence) and much more suddenly in AIDS (through lack of CD4+ T cells)." (PMID 31396143, 2019). "Moreover, 44% of newly diagnosed HIV patients present late for care, defined as a CD4+ T-cell count < 350/mm3, or presentation with an AIDS-defining illness, regardless of CD4 count." (PMID 29514596, 2018). "We examined the changes in timely ART initiation after national ART eligibility criteria were expanded to CD4 ≤ 350 and/or CD4 ≤ 500 in 22 countries, using data on 284,740 adult ART-naïve patients at 171 sites in the International Epidemiology Databases to Evaluate AIDS (IeDEA) network." (PMID 29570723, 2018). "Among them, MSRIST identified baseline CD4 count, age and antiretroviral therapy as the top three most important predictors of survival for the duration of time from HIV diagnosis to AIDS progression and antiretroviral therapy, TB and gender for the duration of time from AIDS diagnosis to death." (PMID 30424736, 2018). "However, it has been recently shown that virological suppression and CD4 cell count fail to protect from the major causes of death of persons living with HIV (PLWHIV), which are mainly non-AIDS-related events, also known as serious non-AIDS events (SNAEs)." (PMID 29807541, 2018). "The co-epidemic of TB with HIV-1/AIDS, characteristically treated as a T cell failure, also involves macrophage dysfunction, as a viral reservoir, but especially when successful HAART restores CD4 T lymphocyte function, resulting in the Immune reconstitution inflammatory syndrome (IRIS)." (PMID 29875747, 2018). "Many patients entered the cohort with advanced immunosuppression, characterized by CD4 + counts below 200 cells/mm3 (32.0%) and presence of AIDS-defining signs and symptoms (45.7%), although most had no record of hospitalization due to HIV in the year prior to entering the cohort (52.7%)." (PMID 30462751, 2018). "Accordingly, the results of the recent START study indicated that absolute CD4+ T cell counts are not predictive for AIDS and non-AIDS events since these events may occur in ART treated patients with absolute CD4 counts >500 cells/μl." (PMID 30459765, 2018). "However, this co-infection cannot explain the whole picture as changes in CD4+ T cell count and HIV viral load that herald progression to AIDS were already evident before the HCV infection occurred, and also the extent of the sequence changes observed can only be explained by HIV superinfection." (PMID 29338738, 2018). "The multivariate logistic regression analysis showed that urban residence, absence of co-morbidity, knowledge about HIV/AIDS, and ART, disclosing HIV status to partner and recent CD4 count ≥ 500 mm3 were significantly associated with adherence to antiretroviral therapy." (PMID 29879913, 2018). "Although HIV transmission from patients with AIDS appears to be most common, the results from this and other studies emphasize that HIV-1 can be transmitted from infected persons who are asymptomatic or minimally symptomatic and who have high CD4+ T cell counts." (PMID 29467460, 2018).
AIDS (continued). "A larger Italian study of patients with suppressed VLs found an elevated risk of non-AIDS mortality in those with CD4:CD8 <0.3 compared with between 0.3 and 0.8, whereas we found little evidence that CD4:CD8 ratio or CD8 count was independently prognostic for non-AIDS mortality." (PMID 28903507, 2017). "Obtaining the baseline CD4 cell count at the start of the ART continues to offer valuable insight of the immune system status for monitoring and long term care management, since early initiation of ART has shown to reduce the hazard ratio for serious AIDS related event." (PMID 29290885, 2017). "There was little evidence that CD4:CD8 ratio or CD8 count was prognostic for non-AIDS mortality." (PMID 28903507, 2017). "HIV diagnoses were adjusted for reporting delay and stratified by the presence of an AIDS-defining event within three months of HIV diagnosis and, for individuals without AIDS, by CD4 cell count (≥500, 350–499, 200–349, <200 cells/mm3) at the time of diagnosis." (PMID 28953320, 2017). "Our finding that both low CD4:CD8 ratio and high CD8 count were associated with AIDS mortality in this population with high CD4 counts and suppressed VLs implies that both CD4:CD8 ratio and CD8 count could account for some excess AIDS mortality in a HIV population that was otherwise healthy." (PMID 28903507, 2017). "Plasma HIV-1 tropism, regardless of how estimated, did not predict the short-term risk of the composite outcome of AIDS or death over 3–12 months from the date of sample, after controlling for co-infection with HCV, age, current viral load, CD4 count and calendar year." (PMID 28129343, 2017). "Another randomised controlled trial, done in Haiti in 2010, compared early ART (initiation of ART within 2 weeks of enrolment into the study) in people with CD4 counts greater than 200 cells per μL and less than 350 cells per μL, with no history of an AIDS-defining illness." (PMID 28063815, 2017). "However, long-term nonprogressors (LTNPs) (≈5% of HIV-1-infected individuals), without progression of AIDS, maintain normal counts of CD4+ T cells (>500 cells/μl) and low viral load (LVL) without ART for many years." (PMID 28222782, 2017). "A similar study at an AIDS research center in Bangkok during 2003–2008 among 799 participants with positive TST results, found that 551 (69.0%) completed 9 months of IPT and participants with baseline CD4 counts >200 cells/mm3 were more likely to complete 9 months of IPT." (PMID 28949995, 2017). "Recent research has shown the causal link between alcohol consumption and the incidence of HIV/AIDS including a better understanding of the pathways through which alcohol use affects ARV adherence (and other medications to treat opportunistic infections) and CD4 counts." (PMID 28975440, 2017). "For the reason that CD4 cell counts and viral load measurements are incomplete in the HIV notification system and are only reported in one-third of the notified cases, the recommended algorithm could only be used with the information about AIDS status." (PMID 28693564, 2017). "Additionally, our cohort generally represents those in established care; DC Cohort participants included in this analysis tended to have relatively high CD4 counts at enrollment (52%) and almost 60% had never had an AIDS diagnosis." (PMID 28982127, 2017). "However, in the START trial, which included only patients who were not immunosuppressed, low CD4:CD8 ratio was associated with the primary endpoint, which included serious AIDS and non-AIDS morbidity as well as all-cause mortality." (PMID 28903507, 2017). "Of 266 newly diagnosed HIV infections in 2015, 46 (17%) cases were diagnosed late (acquired immunodeficiency syndrome (AIDS) or symptomatic non-AIDS stage) and 85/237 (36%) had CD4+ T-cell counts < 350/mL at diagnosis." (PMID 29208160, 2017).
AIDS (continued). "These individuals may all have had acute HIV infections, but we did not confirm this with the CD4+ counts that are typically used to evaluate disease progression to AIDS." (PMID 29110721, 2017). "In the START study, most serious AIDS-related events, serious non-AIDS-related events, or deaths occurred in patients with CD4 counts above 500 cells per μL and the treatment effect was only partly mediated by changes in CD4 cell count during follow-up." (PMID 28063815, 2017). "With the complexity of HIV disease, however, anaemia may be a surrogate marker of some other underlying condition, which may not be captured through categorization with CD4 lymphocyte counts and clinical AIDS diagnosis alone." (PMID 27092270, 2016). "Furthermore, they also consider CD4 T-cell counts of below 350 CD4 cells/μl as a threshold for treatment indication, since ART was found more beneficial regarding a decelerated progression to AIDS and death when initiated at higher CD4-counts." (PMID 27927190, 2016). "PML is believed to be developed exclusively in immunosuppressive patients with significantly higher incidence in patients with AIDS, particularly in AIDS patients without cART and with a low CD4+ lymphocyte count, than in patients with any other immunosuppressive conditions." (PMID 27455335, 2016). "Nonetheless, we compared cases that had CD4 cell count result at first follow-up with those that did not; a minor difference of the proportion of cases that progressed to AIDS at the end of the observation year was found between these two groups (32.2% versus 29.1%)." (PMID 27761466, 2016). "The Strategic Timing of Antiretroviral Treatment (START) study showed that immediate initiation of cART with a CD4+ T-cell count >500 cells/mm3 led to lower rates of serious AIDS-related and non-AIDS-related illnesses and death compared to deferring cART until the CD4 count reached 350 cells/mm3." (PMID 26939611, 2016). "Nevertheless, worldwide and including in resource-rich countries, a rate ranging from 40 to 60% of patients are diagnosed when they have already an AIDS defining disease or a low CD4 count, and these individuals will not benefit from new indications on early therapy." (PMID 27348592, 2016). "Furthermore, incident syphilis cases had marginally higher CD4 count (p = 0.054) and were less likely to have history of AIDS, albeit insignificantly (p = 0.091), compared with the no-syphilis group." (PMID 27992604, 2016). "Older age was strongly associated with cardiovascular mortality, injecting drug use transmission with non-AIDS infection and liver-related mortality, and low CD4 and detectable viral replication ten years after starting antiretroviral therapy with AIDS mortality." (PMID 27525413, 2016). "Furthermore, historical control animals exhibited low to undetectable CD4+ T-cell counts in peripheral blood in as little as 4 weeks following SHIV challenge; this severe and sustained course of pathogenesis led to simian AIDS and animals were euthanized between 38 and 62 weeks postchallenge." (PMID 26958575, 2016). "Globally, the capacity of available CD4 instruments was sufficient to meet the demand of all people living with HIV/AIDS (PLWHA), irrespective of treatment status (4.62 theoretical tests per PLWHA in 2013 [median 7.33; interquartile range (IQR) 3.44–17.75; median absolute deviation (MAD) 4.35])." (PMID 27551917, 2016). "A low CD4/CD8 ratio has already been reported to be associated with certain chronic comorbidities (cardiovascular events, renal failure, Hodgkin diseases, non-AIDS cancers) and with AIDS and non-AIDS mortality." (PMID 27050752, 2016). "These figures may be underestimates, as we only considered the criterion of CD4≤ 200 and not the clinical AIDS-defining conditions, for which we lack data." (PMID 27027505, 2016). "Thus, after CD4+ cell count declines, antiretroviral non-adherence is the strongest predictor for progression to AIDS and, subsequently, death." (PMID 27478681, 2016).
AIDS (continued). "Globally, the capacity of available CD4 instruments was found to be sufficient to meet the demand of all people living with HIV/AIDS (PLWHA), irrespective of treatment status; however, capacity to measure viral load was inadequate to cover needs in most reporting countries." (PMID 27551917, 2016). "penetrans antibodies with the stage of AIDS was recorded; seroprevalence was twofold higher in patients in stage C of disease, according to the CDC classification at the time, than in stage A or B and twofold higher in individuals with a CD4: CD8 ratio less than 0.30." (PMID 27413383, 2016). "However, a higher percentage of men with AIDS (CD4+ T-cell <200/μL) were taking non-HAART antiretroviral therapy (p = 0.006), because HAART was not available when these studies were originally performed." (PMID 27285483, 2016). "However, a small number of HIV-infected individuals are characterized by a slow progression of HIV infection where CD4 counts are maintained above 350 cells/μL without the development of AIDS for decades." (PMID 28050553, 2016). "This clinically asymptomatic stage, which is characterized by persistent HIV replication, systemic immune activation, inflammation, and the gradual depletion of CD4+ T cell, leads to the development of AIDS in the absence of antiretroviral therapeutic interventions." (PMID 26950141, 2016). "The key objective of c-ART is to suppress viral replication and to induce the production of sufficient numbers of CD4+ T cells to prevent AIDS-defining (CD4+ T-cell counts below 200 cells/mm3), and non-AIDS-defining (CD4+ T-cell counts below 500 cells/mm3) severe events." (PMID 27082982, 2016). "A large number subjects are excluded in group two for their AIDS status as diagnosis and without CD4+ T-cell count in first 3 month following diagnosis were excluded for confounding variables, which may have introduced selection bias." (PMID 26413133, 2015). "In addition, the ELPG defined presentation with advanced HIV disease as “Persons presenting for care with a CD4 count below 200 cells/μL or presenting with an AIDS-defining event, regardless of CD4 cell count”23." (PMID 26412578, 2015). "Finally, the recent landmark START study showed a clear benefit to immediate antiretroviral therapy in early asymptomatic HIV infection before a decline in CD4 counts with reductions in both AIDS-related and non-AIDS-related events." (PMID 26641655, 2015). "Both analyses showed a higher risk of death for male gender, year of enrolment before 1993, older age at enrolment, intravenous drug use and the following variables included as time-dependent covariates: low CD4 cell count, AIDS event, cancer occurrence and the absence of antiretroviral therapy." (PMID 25884678, 2015). "Moreover, as noted in the preceding paragraphs, unfavorable alleles of these three IL7R polymorphisms (rs6897932 C, rs987106 T, and rs3194051 A) have been related to low CD4+ T-cells and rapid AIDS progression in Caucasian naïve HIV infected patients and slower CD4+ recovery in patients on cART." (PMID 26123260, 2015). "However this model was not proper to evaluate the cART effect, because of non-independence of cART, CD4 cell count and AIDS event." (PMID 25884678, 2015). "Patients in group 1 (pre-ART CD4+ T cell count ≤ 200/mm3) were slightly older than patients in group 2 (pre-ART CD4+ T cell count > 200/mm3) (38.5 versus 37.0 years, p = 0.09) and, as expected, had experienced more AIDS-defining events (31.8% versus 3.5%, p<0.0001)." (PMID 26636578, 2015). "A further elucidating the molecular mechanism of the interplay among memory CD4 T-cell clonal expansion, effector cell differentiation, and HAART application leads to a gateway towards reconstitution of patient anti-HIV immunity, eradication of HIV, and a cure of AIDS." (PMID 26300920, 2015).